HDAC1 (histone deacetylase 1)
Diseases named in the same sentence as HDAC1 in open-access papers (continued):
Sharing a sentence is not in itself a finding about the gene and the disease.
lung cancer (81 papers, 2007 to 2026). A malignant neoplasm involving the lung. "In patients with advanced lung cancer who have demonstrated resistance to paclitaxel treatment, tumor biopsies show high levels of HDAC-1 and a loss of p21 expression, which correlates with acquired resistance to treatment." (PMID 36263432, 2022). "Pre-clinical studies have demonstrated that HDAC-1 gene expression is associated with lung cancer progression." (PMID 33163495, 2020). "The results in a meta-analysis suggest that HDAC1 may serve as a good diagnostic and prognostic marker for lung cancer." (PMID 38091511, 2022). "A meta-analysis showed that high expression of HDAC1 is associated with poor OS in gastrointestinal and lung cancers, which indicates that HDAC1 may serve as a prognostic signature in these malignancies." (PMID 32807131, 2020). "A meta-analysis showed that the expression level of HDAC1 was closely correlated to the progression and prognosis of lung carcinoma and could be used as a diagnostic and prognostic indicator of lung carcinoma." (PMID 32903420, 2020). "Previously studies showed that HDAC1, locating at chromosome 1p, might serve as a good diagnostic and prognostic marker for lung cancer." (PMID 30710490, 2019). "The development of HDAC1 inhibitors provides a new direction for the treatment of lung cancer, and the combination with chemotherapy, targeted therapy, and immunotherapy can significantly enhance the synergistic anti-tumor effect." (PMID 42290054, 2026). "Abnormal activation of HDAC1 is also one of the core factors for the resistance of lung cancer to chemotherapy, targeted therapy, and immunotherapy." (PMID 42290054, 2026). "HDAC1 is highly expressed in lung cancer, and its expression level is closely related to the malignancy degree, clinical stage, and poor prognosis of lung cancer." (PMID 42290054, 2026). "Earlier DRUGSURV searches found that lung cancer patients with increased HDAC1, HDAC2, and HDAC6 had a poor prognosis." (PMID 40006525, 2025). "Our study embarked on the elucidation of this ambiguity, unveiling that PHF12 collaboratively engages with HDAC1 to propel the proliferation of lung cancer cells." (PMID 39075515, 2024). "In lung cancer, HDAC1 levels were substantially lower in patients with well-differentiated adenocarcinoma than in those with a lower differentiation grade." (PMID 39063083, 2024). "In lung cancer, the actin-binding protein profilin-2 binds to and thereby prevents HDAC1′s access to the promoters of SMAD2 and SMAD3, which causes activation and promotes EMT and angiogenesis in lung cancer cells." (PMID 38279330, 2024). "Lung cancer cell lines expressing high levels of SALL4 are sensitive to the HDAC1 inhibitor Entinostat suggesting the use of this drug as a potential treatment for lung cancer." (PMID 38062245, 2024). "In contrast, the silencing of HDAC1 resulted in reduced expression of the transcription factors, Nanog and Oct4, in lung cancer stem cells and increased sensitivity to cisplatin treatment." (PMID 37144123, 2023). "HDAC-1 mRNA was predominantly expressed in higher-stage (T3 or T4) lung cancer cases, and the strong HDAC-1 immunohistochemical expression (in terms of percentage and intensity) was associated with a remarkably poorer patient OS." (PMID 34441281, 2021). "Treatment with the inhibitor FK228 and silencing HDAC1/2 in lung cancer cells increased the expression of NKG2D ligands." (PMID 34203519, 2021). "A relationship between HDAC1 and lung cancer has been previously emphasized, with HDAC1 suggested as a functional diagnostic and prognostic indicator of lung cancer." (PMID 33596966, 2021). "Study shows that HDAC1 is over-expressed in lung carcinoma and that it is more highly expressed in LSCC than in lung adenocarcinoma." (PMID 32903420, 2020). "PFN2a regulates lung cancer growth through suppressing the nuclear localization of histone deacetylase 1 (HDAC1)." (PMID 31450751, 2019).
lung cancer (continued). "Profilin 2a (PFN2a) is a ubiquitous actin monomer-binding protein and promotes lung cancer growth and metastasis through suppressing the nuclear localization of histone deacetylase 1 (HDAC1)." (PMID 31450751, 2019). "In lung cancer samples, we also observed a significant overexpression of HDAC1, HDAC2, HDAC6 and also DNMT1 and DNMT3A." (PMID 28634396, 2017). "MiR-449a can directly target HDAC1 in primary lung cancer and inhibit cell growth and anchorage-independent growth." (PMID 26975503, 2016). "We recently demonstrated that the Groucho TLE1 is a novel corepressor which represses E-cadherin in lung cancer cells, in part by recruiting HDAC1 to the E-cadherin promoter." (PMID 27655370, 2016). "In this study, we determined the mechanism underlying the ability of Daxx to suppress hypoxia-induced lung cancer metastasis, showing that Daxx acts through the HIF-1α/HDAC1/Slug pathway." (PMID 28004751, 2016). "In summary, we demonstrated that Daxx plays a pivotal role in hypoxia-induced cancer cell dissemination and invasion by regulating the HIF-1α/HDAC1/Slug and E-cadherin pathway in lung cancer." (PMID 28004751, 2016). "Several studies have shown that class I and II HDACs (HDAC1-10) are overexpressed in some cancers, including gastric cancer, colorectal cancer, prostate cancer, and lung cancer." (PMID 25605253, 2015). "For example, we found two somatic pseudogene copies of HDAC1, one in a colorectal cancer and one in a lung cancer." (PMID 24714652, 2014). "HDAC1 is a target of miR-449, a recent study showed that in lung cancer, miR-449 has a synergistic effect on growth arrest with HDAC inhibitor, providing new information about combination therapy with miRNA and c-Met inhibitors." (PMID 23734217, 2013). "Inhibition of HDAC1 was suggested to serve as a way of enhancing the radiosensitivity in lung cancer and esophageal cancer." (PMID 23614048, 2013). "Recently, Jeon and colleagues found that miR-449a/b has reduced expression in lung cancer tissues, with the target gene HDAC1 overexpressed at mRNA level." (PMID 23734217, 2013). "Clinically, lung cancer patients with high HDAC1, HDAC2, and HDAC6 levels have a poor prognosis." (PMID 40732250, 2025). "In addition, HDAC1 maintains lung cancer cell stemness and induces a drug-resistant phenotype in lung cancer cells by inhibiting miR-200b expression and reducing the targeting of miR-200b to Suz12." (PMID 37144123, 2023). "Histone deacetylase 1 (HDAC1) is highly expressed in cisplatin-resistant lung cancer cells." (PMID 37144123, 2023). "Still, little is known about the relationship between EGFR and HDAC1, specifically in lung cancer." (PMID 33976119, 2021). "In addition, the expression of HDAC1 has been reported to be reversely correlated with the overall survival of patients with lung cancer." (PMID 33596966, 2021). "HDAC1 is highly expressed in various tumors including lung carcinoma." (PMID 32903420, 2020). "SUMOylation could enhance the transcriptional repression activity of Slug via recruiting more HDAC1, resulting in reduced expression of downstream Slug target genes and enhanced lung cancer metastasis." (PMID 30612578, 2019). "Ubc9/PIASy-mediated Slug SUMOylation and subsequent HDAC1 recruitment may play a crucial role in hypoxia-induced lung cancer progression, and these processes may serve as therapeutic targets for NSCLC." (PMID 30612578, 2019). "Previous research demonstrated that HDAC1, a histone deacetylase, could bind to Smad3 promoter region in lung cancer cells to suppress Smad3 expression in human lung cancer cells." (PMID 28598443, 2017). "We set out to investigate the co-expression of HDAC1 and HDAC2 in lung cancer cell lines and to use an unbiased siRNA screen to identify DUBs that may regulate HDAC1 and/or HDAC2 expression." (PMID 25970771, 2015). "Thus, HDAC1 represses RhoB expression in lung cancer cells and treatment with the HDAC inhibitor, trapoxin A enhanced the transcription and expression of RhoB mRNAs." (PMID 25548921, 2014).
lung cancer (continued). "As a consequence of this, the reduction of miR-449a may in part explain why levels of HDAC1 are frequently overexpressed in lung cancer." (PMID 24212667, 2011). "Moreover, HDAC1 expression in lung cancer tissues has been shown to be correlated with cancer progression." (PMID 18047684, 2007). "Our findings suggest that five genes (SETDB1, TWIST1, HDAC1, SP1, and GRIA2) are likely involved in the dystropic relationship observed between Huntington’s disease and non–small cell lung cancer." (PMID 40843670, 2025). "In lung cancer, SOX2 interacts with HDAC1 to inhibit SOX9 expression, while inhibition of HDAC1 increases SOX9 expression." (PMID 39372390, 2024). "HDAC11 has an effect similar to that of HDAC1, which is highly expressed in the cancer stem cell population of LUAD, resulting in enhanced self-renewal of lung cancer stem cells and interaction with GLI1 to upregulate SOX2 expression." (PMID 37144123, 2023). "Abnormal expression of histone deacetylases (HDACs) is often reported in various types of cancers, e.g., overexpression of HDAC1-3 in ovarian cancer, overexpression of HDAC 1 and 3 in lung cancer and overexpression of HDAC2 in gastric cancer." (PMID 37101287, 2023). "According to our in silico search using DRUGSURV,high levels of HDAC1, 2, or 6 were remarkably correlated with poorsurvival (p < 0.05) in GEO datasets (GSE31210,GSE11969, and GSE36471, respectively) of lung cancer patients." (PMID 37854628, 2023). "Another member of the SNAI family, Slug, forms a complex with G9a and histone deacetylase 1, 2, and 3 (HDAC1, 2, and 3) in HCC and lung cancer." (PMID 35740522, 2022). "We observed that treatment with FK228, which is a selective HDAC1/2 inhibitor, also known as Romidepsin, induced NKG2D ligand expression at the transcriptional and proteomic levels in two different lung cancer cell lines." (PMID 34203519, 2021). "In previous studies, HDAC1 was indirectly involved in the epigenetic regulation of P38 MAPK, which drives lung cancer progression." (PMID 33345444, 2021). "In lung cancer, a report has shown that DAXX can inhibit cancer cell metastasis by directly blocking the HIF1a/HDAC1/Slug signaling pathway." (PMID 31942198, 2020). "Another regulation of Smad2/3 proteins showed that profilin-2 interacts with HDAC1 to inhibit the binding of HDAC1 to the promoters of Smad2 and Smad3, leading to their activation and enhancing the TGF-β-induced EMT and angiogenesis in lung cancer cells." (PMID 32114978, 2020). "Conversely, HDAC1 knockdown by shRNAs increased promoter-bound H3K14Ac and PDLIM2 transcription in human lung cancer cells." (PMID 31757943, 2019). "As an HDACi, entinostat preferentially inhibits HDAC1 as compared to HDAC3, and has been used in clinical trials to treat lung cancer patients." (PMID 27705911, 2016). "Our data show coordinated transcription of HDAC1 and HDAC2 in lung cancer cell lines, but suggest HDAC2 protein expression is cell-context specific." (PMID 25970771, 2015). "Compounds 9a-d selectively inhibited HDAC6 (IC50 = 0.1–1.0μM) over HDAC1 (IC50 = 0.9–6μM) and moreover, also selectively inhibited the growth of lung cancer cells vs. patient matched normal cells." (PMID 26698121, 2015). "X-radiation and siRNA inhibit expression of HDAC1 and HDAC2, weaken the inhibitory effect of HDAC on Axin, upregulate Axin expression and induce apoptosis of lung cancer cells." (PMID 23110995, 2012). "In lung cancer, MCM5 interacted with histone deacetylase 1 (HDAC1) to aggravate cancer progression." (PMID 40695783, 2025). "Scriptaid targets HDAC1, 2, and 8, and HDAC6 of Class IIb and has been developed as a potent HDACi with anti-tumour activity against several cancers such as endometrial, ovarian, colon or lung cancer." (PMID 35632748, 2022).
lung cancer (continued). "In lung cancer, Daxx inhibits lung metastasis by suppressing the HIF-1α/HDAC1/Slug pathway." (PMID 34359912, 2021). "Importantly, the opposite expression pattern (higher HDAC1 and lower OAZ1) correlated with bad treatment response and poor overall survival than other groups in lung cancer." (PMID 31127087, 2019). "Importantly, the opposite expression pattern (higher HDAC1 and lower p21) correlated with bad treatment response, short time to tumor progression (TTP) and poor overall survival than other groups in lung cancer." (PMID 26794658, 2016). "Statistical analysis data indicated that there was a negative correlation between HDAC1 and p21 in lung cancer tissues (P<0.05)." (PMID 26794658, 2016). "Notably, AS-IV significantly upregulates MCM5 in both lung cancer cells and tissues; MCM5 and HDAC1 facilitate the proliferation and migration of lung cancer cells, whereas AS-IV restores the expression of E-cadherin, hence suppressing lung cancer cell activity." (PMID 39064966, 2024). "Similar results were obtained when the expression of both HDAC1 or HDAC2 was inhibited, suggesting that suppressing HDAC1 and HDAC2 expression both genetically and pharmacologically leads to activation of NKG2D ligands and facilitate NK cell-mediated anti-tumor effects in lung cancer." (PMID 39161385, 2024). "Therefore, HDAC1 and HDAC2 play a central role in the transcription of NKG2D ligands, and the specific inhibition of HDAC1 and HDAC2 might be a new strategy for treating lung cancer by promoting NK cell-mediated anticancer immunity." (PMID 34203519, 2021). "Besides no record about SCN8A, THPA confirmed a similar tendency for an increased expression of HDAC1, DLG1, EPHB2 and CALB1, while GDNF was not apparently changed in either normal or lung cancer tissues; no data were available for SCN8A." (PMID 32102656, 2020).
colorectal cancer (54 papers, 2006 to 2026). A primary or metastatic malignant neoplasm that affects the colon or rectum. "In a recent meta-analysis, the expression level of HDAC1 in colorectal cancer was found to be higher and closely associated with tumor stage and tumor grade than that in noncancerous tissue." (PMID 35008525, 2021). "Induction of HDAC1, 2, 3 expression levels also implicated significantly reduced patient survival in colorectal cancer." (PMID 22496786, 2012). "Furthermore, HDAC1 overexpression was found to be associated with advanced tumor stage and poor survival in gastric and colorectal cancers." (PMID 37553876, 2023). "In ovarian cancer, CBP/p300 overexpression correlates with enhanced H3K18 lactylation and aggressive glycolysis, while HDAC1 downregulation in colorectal cancer promotes Treg cell-mediated immunosuppression via sustained histone lactylation." (PMID 40755753, 2025). "Recent studies have shown that Vorinostat and Butyrate (targeting HDAC1, 2, 3, 8) can significantly increase the expression levels of β2M and HLA-class I in various Colorectal Cancer-Cancer Initiating Cells (CRC-CICs)." (PMID 40573881, 2025). "SFN affects human telomere reverse transcriptase (hTERT) mRNA levels by regulating colorectal cancer cells histone deacetylase 1 (HDAC1), which reduces hTERT protein expression and enzyme activity and induces apoptosis." (PMID 38902597, 2024). "HDAC1 is a histone deacetylase and a prognostic marker for colorectal cancer involved in epigenetic regulation via transcriptional repression." (PMID 35963857, 2022). "The compounds potently inhibited BRAFV600E, HDAC1, and HDAC6 enzymes and suppressed the proliferation of colorectal cancer cells harboring both wide-type BRAF and V600E mutated BRAF." (PMID 35936102, 2022). "For example, HDAC1 has been demonstrated to be tumor promoter in a range of malignancies, covering gastrointestinal tumors such as colorectal cancer, and gastric cancer, as well as HCC and ovarian cancer." (PMID 35395834, 2022). "HDAC1 is a member of the HDACs family and can promote the tumor angiogenesis and the resultant colorectal cancer tumorigenesis." (PMID 35395834, 2022). "Mechanistically, HDAC2 promotes epithelial‐mesenchymal transition (EMT) in colorectal cancer cells by combining HDAC1 with EZH2 (a key histone methyltransferase), possibly through the modular scaffold function of a new lncRNA, ENSG00000274093.1." (PMID 33325150, 2021). "The mechanistic study showed that SOX4 directly binds to the promoter of HDAC1, promotes HDAC1 transcription, thereby supporting the stemness of colorectal cancer cells." (PMID 33482915, 2021). "HDAC1 hallmarks colorectal cancer stem cells and depletion of HDAC1 abolished the stimulatory effect of SOX4." (PMID 33482915, 2021). "For example, TCF7L1 has been reported to recruit CtBP and HDAC1 to epigenetically repress tumor-suppressor DICKKOPF4 gene in colorectal cancer cells." (PMID 30811526, 2019). "In general, butyrate inhibits most HDACs, except class 2 (HDAC6 and 10) and class 3, and specifically inhibits HDAC1 and 3 in colorectal cancer cells." (PMID 29930765, 2018). "Knockdown of either HDAC1 or HDAC2 in liver and colorectal cancer cell lines has little effect on cell viability and proliferation, whereas combined knockdown of HDAC1 and HDAC2 increases cell death and reduces cell proliferation." (PMID 29899862, 2018). "The expression level of HDAC1 in colorectal cancer was higher than that in control tissue samples (OR = 10.84, 95% CI = 5.33–22.07, P < 0.00001)." (PMID 28424407, 2017). "In this analysis, we found that HDAC1 expression in colorectal cancer tissues is higher than that in normal tissues." (PMID 28424407, 2017).